RELN (reelin)
Diseases named in the same sentence as RELN in open-access papers (continued):
Sharing a sentence is not in itself a finding about the gene and the disease.
schizophrenia (continued). "Nevertheless, we found a number of genes in this list that have a reported association to schizophrenia or other neuropsychiatric disorders, for example, TENM4, NXN, NRXN1, GALNT5, SHANK3 and RELN." (PMID 36711134, 2022). "RELN is one of the more extensively examined schizophrenia candidate genes." (PMID 32082176, 2020). "Another therapeutic approach to the treatment of Reelin dysregulation in schizophrenia may be the inhibition of the enzyme that degrades Reelin." (PMID 32982694, 2020). "While these pathways are significant to neural function and synaptic connectivity, the extracellular matrix is of particular interest with regard to psychiatric disorders, such as schizophrenia, as components of these systems, including reelin (RELN), are known to participate." (PMID 32325711, 2020). "For example, hypermethylation levels of the 5′ region of RELN promoter, leading to lower Reelin production, have been described, although with some discrepancies, in autism, temporal lobe epilepsy, and schizophrenia." (PMID 32438605, 2020). "In the current study, we generated a novel Reln‐del mouse model to mimic the Japanese subject with schizophrenia harboring the specific exonic deletion in RELN and compared it with the findings of previous studies on other reeler‐associated models, including Orleans reeler mice." (PMID 32065683, 2020). "Although this is quite speculative at the moment, it would be of interest to evaluate considering that levels of reelin levels in the brains of schizophrenia patients are nearly 50% downregulated in comparison to controls." (PMID 32982757, 2020). "Furthermore, hippocampal Reelin levels are down-regulated in the brains of both schizophrenic patients and in rodent models of schizophrenia." (PMID 32982694, 2020). "RELN is an extensively studied schizophrenia candidate gene." (PMID 32082176, 2020). "Similarly, epigenomic changes in the schizophrenia candidate gene RELN is also supported by its relationship with the cognitive function of schizophrenia patients." (PMID 32764320, 2020). "Moreover, the reduction of reelin levels in post-mortem schizophrenia brains was reported to be approximately 50%, comparable to the levels in HRM, rather than complete depletion." (PMID 32580454, 2020). "Given its role in neurodevelopment and postulated role in schizophrenia, reelin may be one such factor." (PMID 32580454, 2020). "Reelin interacts with several cellular receptors, and a lack of reelin interaction is associated with the appearance of neuropsychiatric diseases such as AD and schizophrenia." (PMID 32150898, 2020). "The levels of Reelin protein and mRNA are reduced approximately two-fold in brain extracts from patients with chronic psychosis like schizophrenia and autism, maybe due to hypermethylation of the promoter region." (PMID 32604886, 2020). "RELN plays an important role in the etiology of schizophrenia." (PMID 32082176, 2020). "Interestingly, reelin supplementation restored sensory motor gating and synaptic plasticity and reduced association learning deficits in HRM and schizophrenia-like symptoms." (PMID 32116553, 2019). "For example, decreased expression of reelin is a common characteristic among neurological and mental disorders such as autism, schizophrenia, depression and bipolar disorder, and knock-out mice lacking aggrecan demonstrated improvement in memory in spontaneous object recognition test." (PMID 31632233, 2019). "This is an important direction for future studies as reelin deficiency as well as stress and related HPA–axis dysregulation play a major role in the pathophysiology of numerous mental disorders, such as MDD or schizophrenia." (PMID 29941797, 2018). "Our finding of female-specific susceptibility to reelin deficiency is supported by studies showing that a single nucleotide polymorphism (SNP) with the RELN gene sequence increases the risk of schizophrenia in women, but not in men." (PMID 29941797, 2018).
schizophrenia (continued). "In addition, multiple candidate genes implicated in schizophrenia or other psychiatric disorders were detected, such as SST, NPY, SLC32A1, HINT1, RELN, and IFITM3." (PMID 29958387, 2018). "Notably, Reelin expression was found to be decreased in interstitial white matter neurons, in a study that also confirmed increased density of these neurons in schizophrenia." (PMID 26839720, 2016). "In addition, Fatemi’s group also showed that a downregulation of reelin in the hippocampus occurred not only in schizophrenia and bipolar disorder, but also in patients with depression." (PMID 26941609, 2016). "In particular, these data indicated that the loss of Reelin CTR and/or reduced Reelin signaling could be the direct cause of some symptoms observed in schizophrenia, bipolar disorder, or ASD." (PMID 27346785, 2016). "This led to the idea of a co-occurrence of reelin disturbances in autism and schizophrenia." (PMID 26941609, 2016). "In addition to genetic variation, epigenetic control of RELN gene expression has also been called into play, initially by studies focused on schizophrenia." (PMID 27134686, 2016). "Moreover, overexpression of reelin prevents the manifestation of behavioral phenotypes related to schizophrenia." (PMID 26968981, 2016). "The aim of this study was to utilize patient-derived olfactory neurosphere-derived (ONS) cells to investigate whether extracellular reelin alters cell motility in schizophrenia patient-derived cells." (PMID 27602387, 2016). "We and others have shown that altered RELN expression in schizophrenia (SZ) and bipolar (BP) disorder patients is difficult to reconcile with classical Mendelian genetic disorders and it is instead plausible to associate these disorders with altered epigenetic homeostasis." (PMID 27092053, 2016). "We conclude that the reelin protein blood concentration might be a relevant signal with respect to the pathophysiology of schizophrenia." (PMID 26305216, 2015). "Our finding is in line with the only other study analyzing blood RELN signal in schizophrenia." (PMID 26305216, 2015). "The possible meaning of our finding: Taking together all available data and our findings there is ample evidence to support the notion that the RELN system might well play an important role in the pathophysiology of schizophrenia." (PMID 26305216, 2015). "Our findings point to a relevant role of reelin metabolism in the pathogenesis of schizophrenia.Reelin could be a biomarker for the course of disease or psychopharmacological treatment." (PMID 26305216, 2015). "We do not have the parental genotypes for the samplesanalyzed in this study; however, one possible explanation for the observed allelicimbalance of RELN in schizophrenia might be defects in imprintingerasure in the adult brain." (PMID 21603580, 2011). "Interestingly, we found many neuron or schizophrenia related pathways, such as axonal guidance signaling and reelin signaling in neurons." (PMID 20156358, 2010). "Reelin is down-regulated in schizophrenia, autism, and mood disorders, showing a general decrease in different brain areas in schizophrenia, autism, and bipolar disorder, while there could be a more specific decrease in major depressive disorder." (PMID 20414372, 2010). "Because reelin plays a role in neuronal migration and synaptic plasticity in the cerebral cortex, the reduction of reelin in schizophrenia would indicate a neurodevelopmental abnormality that induces a GABAergic deficit in schizophrenia." (PMID 18439259, 2008). "Mithramycin induced a time dependent decrease in mRNA and protein levels of complex I subunits NDUFV1, NDUFV2 and NDUFS1, as well as of reelin, which was arbitrarily chosen as a gene known to be modulated by Sp1 and repeatedly reported to be abnormally expressed in schizophrenia." (PMID 17786189, 2007). "Hence, the exact role of the RELN gene in the pathophysiology of schizophrenia cannot be derived." (PMID 39897195, 2025).
schizophrenia (continued). "However, in recent decades, its role in the adult brain has become increasingly important, and it is now clear that diminished Reelin function is involved in the pathogenesis and progression of neuropsychiatric and neurodegenerative disorders, including schizophrenia and Alzheimer’s disease (AD)." (PMID 39931643, 2025). "RELN may play a role in the emergence of neurodevelopmental diseases such as schizophrenia." (PMID 39897195, 2025). "Therefore, 5mC is an important factor in regulating RELN expression, and exploring the precise mechanism of the methylation of RELN may help elucidate the pathogenesis of schizophrenia." (PMID 38203806, 2024). "Moreover, the monitoring of DNA methylation related to reelin expression might be used as a marker in assessing the severity of the symptoms appearing in schizophrenia." (PMID 38137152, 2023). "Reelin is a large secreted ECM glycoprotein regulating many important processes in mammalian brain development, and dysregulation of reelin signaling has been linked to several brain diseases such as autism, schizophrenia, depression, AD, and, in particular, epilepsy." (PMID 35733853, 2022). "However, it remains unclear through which neurotransmitter mechanisms reelin plays a role in schizophrenia." (PMID 32580454, 2020). "Moreover, since RELN is crucial in the genetic etiology of schizophrenia, our study could find new possibilities for novel drug targets for schizophrenia." (PMID 32082176, 2020). "Clinical evidence supports increased methyl donor S-adenosylmethionine in the brains of patients with schizophrenia, and an association between hypermethylation of the RELN promoter and down-regulation of the corresponding protein (Reelin) in the brains of these patients." (PMID 32982694, 2020). "Cell motility was quantified in the presence of extracellular reelin using automated imaging and analysis of living cells in a 96-well format, providing a non-biased quantification of large numbers of cells from nine patients with schizophrenia and nine healthy controls." (PMID 27602387, 2016). "Briefly, the effects of reelin on behavior and its connections to schizophrenia and depression may be realized through multiple pathways, from alterations in glutamate signaling and synapse regulation to widespread neurodevelopmental effects related to neuronal migration." (PMID 25762938, 2015). "Therefore, some interaction between the NRG1-ErbB4 signaling and other schizophrenia-related genes such as Reelin might occur during development." (PMID 26733804, 2015). "However, the fact that cortical layering appears to be fairly intact in most cortical areas in schizophrenia, is not consistent with a major loss of function of the reelin gene early in development." (PMID 23720610, 2013). "Furthermore, decreased level of reelin expression in the hippocampus is related to schizophrenia." (PMID 22174859, 2011). "Besides, hypermethylation of the reelin promoter in patients with schizophrenia has been reported." (PMID 20421980, 2010). "Plasma and cerebrospinal Reelin concentrations are generally reported to be reduced in ASD and schizophrenia but variably altered in Alzheimer's disease." (PMID 41416042, 2025). "The reduction of reelin and GAD-67 in the prefrontal neurons of schizophrenia brains seems to be the consequence of the epigenetic hypermethylation of their promoters by the overexpression of DNA-methyltransferase 1 (DNMT1)." (PMID 38137152, 2023). "Clozapine, but not haloperidol or risperidone, corrects behavioural phenotypes and normalized the DNMT1 level and 5-mC promoter hypermethylation of schizophrenia-related genes (GAD1, RELN, BDNF) in the PRS animal models." (PMID 36979236, 2023). "Dysfunction of the reelin signaling pathway has been found in ASD, schizophrenia, epilepsy, bipolar disorder, mental retardation, depression, Alzheimer’s disease, and lissencephaly." (PMID 35705542, 2022).
schizophrenia (continued). "The reelin haploinsufficient heterozygous reeler mice (HRM), an animal model of schizophrenia, have altered mesolimbic dopaminergic pathways and share similar neurochemical and behavioral properties with patients with schizophrenia." (PMID 32116553, 2019). "The LIMMA analysis first detected a number of down-regulated genes in individuals with EDs that are known to be suppressed in schizophrenia or major depressive disorder, such as SST, NPY, SLC32A1, HINT1, and RELN." (PMID 29958387, 2018). "This prominent physiological role immediately links abnormal reelin expression to many neurodevelopmental and psychiatric disorders, including ASD, schizophrenia, bipolar disorder, major depression, and Alzheimer’s disease." (PMID 27134686, 2016). "For instance, the N-glycosylation patterns of Reelin and acetylcholinesterase were found to be changed in AD, as were those of the GABAA receptor subunits in schizophrenia." (PMID 27259237, 2016). "Altogether, the evidence suggests a relationship between epigenetic alterations induced by PNS on the reelin gene, with PFC impairment observed in schizophrenia." (PMID 26968981, 2016). "The reelin (RLN) gene was differentially methylated in individuals with schizophrenia using an MWAS, as it was for schizophrenia and bipolar disorder in a MWAS of brain regions, replicating previous findings." (PMID 25229548, 2014). "DNMT1 up-regulation is suggested to induce hyper-methylation and down-regulation of RELN and the GABA synthesizing enzyme GAD67 in prefrontal inter-neurons of schizophrenia patients." (PMID 21358990, 2010). "Reduced gene and protein expression of Reelin (RELN) and up-regulation of neural cell adhesion molecule (NCAM) is noted in schizophrenia." (PMID 16846510, 2006). "Our results showed that RELN mRNA expression levels were not statistically significant in patients with schizophrenia after antipsychotic treatment." (PMID 39897195, 2025). "The role of Reelin in inflammation was recently reviewed; however, the various disorders marked by both low Reelin expression and elevated markers of inflammation, such as major depression, schizophrenia, and Alzheimer’s disease, were not considered." (PMID 38482060, 2024). "Furthermore, RELN, RGS4, ERBB3, and GSK3 gene expression was downregulated in the olfactory neurosphere-derived (ONS) cells of schizophrenia patients." (PMID 34502224, 2021). "Our findings do not exclude a role of reelin in schizophrenia via other neurotransmitter pathways e.g. glutamate." (PMID 32580454, 2020). "It should be noted that LRP8 has non-synaptic functions of credible relevance to schizophrenia, including mediating reelin-related functions on neuronal migration, neurogenesis and neuronal differentiation." (PMID 31691811, 2020). "In the present study, Reelin injection into the hippocampus reversed impairments in object recognition memory and anxiety-like behavior, as well as the decreased in synaptoporin-immunoreactive area in the hippocampus, in an MIA animal model of schizophrenia." (PMID 32982694, 2020). "The signaling protein roles of RELN in the migration of neurons and neural connection could explain the RELN abnormalities in patients with ASD along with Alzheimer’s disease, schizophrenia, lissencephaly, and bipolar disease." (PMID 32244359, 2020). "Overall, these data do not support a role of reelin in schizophrenia, at least not in HRM and in the methamphetamine sensitisation model." (PMID 32580454, 2020). "In conclusion, these data do not support a role of reelin in schizophrenia, at least not in HRM and in the methamphetamine sensitisation model." (PMID 32580454, 2020). "This contributes to increased expression of reelin and GAD67 in cortical GABAergic interneurons which may reduce aggression, as downregulation of reelin and GAD67 has been observed in patients with schizophrenia and bipolar disorder." (PMID 30581496, 2018).
schizophrenia (continued). "Patients suffering from psychiatric disorders such as schizophrenia, bipolar disorder, major depression, and autism spectrum disorders (ASDs) exhibit an approximate reelin downregulation of 50% in several brain structures, most notably the hippocampus and PFC." (PMID 28127276, 2016). "On the other hand, the heterozygous reeler mouse (HRM), which has 50 % expression of reelin and is used as a model for schizophrenia, does not have the inversion of the cortical layers observed in homozygous reeler mice." (PMID 26968981, 2016). "The reduced or complete lack of reelin signaling impairs neuronal connectivity and synaptic plasticity leading ultimately to the cognitive deficits present in autism and schizophrenia." (PMID 23700474, 2013). "Notably, the heterozygous reeler mouse, which has 50% reduction of RELN protein, exhibits altered cortical circuits without disturbed layering and is considered a model for schizophrenia." (PMID 38980724, 2024). "Thus, CRMP1 could be a novel candidate protein for the investigation of schizophrenia mechanisms, which functionally interact with DISC-1 and intersect with the reelin and DISC-1 pathways." (PMID 36430976, 2022). "There is a need to determine whether changes in RELN mRNA expression in SCZ patients are the result of long-term antipsychotic treatment rather than the etiological characteristics of schizophrenia." (PMID 33158463, 2020). "Studies on schizophrenia, autism spectrum disorders, mood disorders, Alzheimer's disease, and epilepsy point to the involvement of ECM molecules such as chondroitin sulfate proteoglycans, Reelin, and matrix metalloproteases, as well as their cell surface receptors." (PMID 26839720, 2016). "Moreover, unlike in reeler, reelin protein was still detected in schizophrenia patient brains, albeit at a lower level compared with healthy controls." (PMID 27602387, 2016). "Recent analyses of the methylation arrays of postmortem brain samples indicated that the hypermethylation of RELN, hypermethylation and down-regulated transcription of SOX10, and hypomethylation of MB-COMT promoters may contribute to the development of schizophrenia." (PMID 28117656, 2016). "Therefore, it is very likely that the full activity of Reelin, exerted by Reelin with intact CTR, is required for normal working memory function and that its deficit can lead to onset or deterioration of neuropsychiatric disorders such as schizophrenia." (PMID 27346785, 2016). "On the basis of this findings and considering the preceding studies we hypothesized altered blood RELN concentration in schizophrenia without prediction the direction of alteration." (PMID 26305216, 2015). "Depending on the features of environmental factors and the time-window of insult interacting with reelin expression, an individual could thus develop one neurodevelopmental disorder rather than another one (i.e., schizophrenia versus ASD)." (PMID 25237666, 2014). "For instance hyper- DNA methylation of RELN, SOX10 [SRY (sex determining region Y)-box 10], FOXP2 (forkhead box P2), and HTR2A as well as hypo- DNA methylation of MB-COMT (membrane-bound catechol-O-methyltransferase) and HTR2A have been reported in schizophrenia." (PMID 25206360, 2014). "Further, no studies to date have evaluated epigenetic changes in the Reelin pathway in a MIA model, despite this finding being evidenced in schizophrenia postmortem studies." (PMID 36979424, 2023). "This study indicates a possible, comprehensive relationship between the effects of neurofeedback add-on therapy with an increase in reelin serum level and an improvement of neurocognitive functions as well as a reduction in negative and general symptoms of PANSS in patients with schizophrenia." (PMID 39064075, 2024). "Note however that this model does not imply that reelin is the only link between PNS and schizophrenia, as other PNS-regulated genes like GAD67 and BDNF may also impact on the symptomatology of schizophrenia." (PMID 26968981, 2016).